TNF (tumor necrosis factor)
Diseases named in the same sentence as TNF in open-access papers (continued):
Sharing a sentence is not in itself a finding about the gene and the disease.
anorexia nervosa (9 papers, 2016 to 2025). A disorder most often seen in adolescent females characterized by a refusal to maintain a minimally normal body weight, an intense fear of gaining weight, a disturbance in body image, and, in postmenarcheal females, the development of amenorrhea. "In patients with anorexia nervosa, an increase in pro-inflammatory cytokines, such as interleukin-1β (IL-1β), tumor necrosis factor-α (TNF-α), and interleukin-6 (IL-6), have also been reported." (PMID 35215322, 2022). "Specifically, research is suggestive of increased levels of various pro-inflammatory cytokines as well as the spontaneous production of tumor necrosis factor in anorexia nervosa; genetic studies further support a dysregulated immune system in this disorder." (PMID 31717370, 2019). "Curiously, there is a case report of an individual with long-standing juvenile idiopathic arthritis and anorexia nervosa who exhibited improvement in body weight and appetite after treatment with infliximab (anti-TNF therapy)." (PMID 31717370, 2019). "Studies have shown that rats transfected with the human TNF-α gene exhibit anorexia nervosa." (PMID 37533569, 2023). "Studies examining tumor necrosis factor (TNF) levels have also resulted in decreased, unchanged, or increased levels of this cytokine, but a majority of the studies suggest increased secretion of TNF by immune cells in anorexia nervosa." (PMID 31717370, 2019). "Furthermore, research is suggestive of increased spontaneous production of TNF from circulating monocytes and lymphocytes in individuals with anorexia nervosa when studied in vitro." (PMID 31717370, 2019). "Indeed, meta-analyses have found elevated levels of TNF in anorexia nervosa when compared to the controls (p = 0.008, p = 0.015)." (PMID 31717370, 2019). "Moreover, inflammatory markers such as IL6 or TNFα are enhanced in haemodialysis patients with or without appetite loss, and in anorexia nervosa patients." (PMID 31878925, 2019).
autoimmune encephalitis (9 papers, 2012 to 2025). Inflammation of the brain secondary to an immune response triggered by the body itself. "In a model of autoimmune encephalitis, the different roles of type 1 and type 2 receptors for TNF have been demonstrated." (PMID 31906244, 2019). "Blocking Kvs reduces IL-2 and tumor necrosis factor production, resulting in improved autoimmune encephalitis and the inhibition of microglial-mediated neuronal death in experimental models." (PMID 25852770, 2015). "In mouse models of autoimmune encephalitis, PD‐1+ TRM produced IFN‐γ, TNF, Granzyme B, and perforin, and immunohistochemistry revealed a close interaction between TRM and neurons expressing self‐antigens, leading to neuronal loss and focal neuroinflammation." (PMID 41388658, 2025). "In another mouse model of autoimmune encephalitis, TRM, when exposed to self‐antigens, proliferated, expressed degranulation markers like CD107a, and co‐produced IFN‐γ and TNF." (PMID 41388658, 2025).
chronic GvHD (9 papers, 2010 to 2024). "Associated with T lymphocytes, IFNγ and TNFα are core cytokines of chronic GvHD pathogenesis, and IL-6 and IL-22 aggravate skin lesions." (PMID 39131155, 2024). "Since all the patients who underwent chronic GvHD were in the TNF low group, logLik converged before factor ‘TNF fold increase,’ making the coefficient <10–8 in a Cox model both for cGvHD and for moderate to severe cGvHD." (PMID 35463028, 2022). "In fact, anti-TNF-α therapy with infliximab and etanercept is used to treat steroid-refractory chronic GvHD." (PMID 31921162, 2019). "Furthermore, MSCs can promote the down-modulation of several DC maturation markers and inhibit TNF-α secretion, leading to an immunological tolerance state, which can be beneficial for many diseases, for instance, chronic graft versus host disease." (PMID 24846008, 2014). "The PSGL1hi Th1, Th2, and Th17 cross-reactive autoreactive Trm cells interact with DCs and macrophages to mediate chronic GVHD pathogenesis via their production of cytokines such as TGF-β, IFN-γ, TNF-α, IL-4, IL-17, and IL-22." (PMID 34539630, 2021). "However the proportion of CD4+ T cells generating cytokines, such as TNF-α, TGF-β, IL-21 and IL-13, which are critically involved in chronic GVHD, was significantly reduced in mLN from CpG-proB recipients, while only IL-13-expressing CD4+ T cells were diminished in pLN." (PMID 35479094, 2022).
congenital heart disease (9 papers, 2007 to 2025). A heart disease that is present at birth. "The aim of the present study is to investigate the ghrelin in congenital heart disease and the association of ghrelin with TNF-α and IL-6.Materials and methods." (PMID 18274638, 2007). "The G/A+A/A genotypes have also been reported to be major producers of TNF-α in congenital heart disease." (PMID 34290697, 2021). "In comparison to controls, serum ghrelin, TNF-α levels were significantly higher in acyanotic patients and cyanotic patients with congenital heart disease (P<.0001)." (PMID 18274638, 2007). "In acyanotic and cyanotic patients with congenital heart disease, there was a positive correlation between ghrelin and TNF-α (r=.485, P<.05 and r=.573, P<.01, resp)." (PMID 18274638, 2007). "We measured serum ghrelin, TNF-α, and IL-6 levels using spesific immunoassay in 68 patients (47 acyanotic, 21 cyanotic with congenital heart disease) and in 25 control subjects.Results." (PMID 18274638, 2007). "The objective of this study is to investigate and compare the functional role of ghrelin on the regulation of energy balance in children with cyanotic and acyanotic congenital heart disease and the association of ghrelin with TNF-α, IL-6, that were not entirely confirmed in literature by now." (PMID 18274638, 2007). "Tortuous vessels are commonly seen after injection of TNFα in mice, in a rat model of Oxygen Induced Retinopathy (OIR) and in patients with cyanotic congenital heart disease." (PMID 25203538, 2014).
conjunctivitis (9 papers, 2019 to 2025). Inflammation of the conjunctiva of the eye. "Oral administration of Lactobacillus plantarum NK151, Bifidobacterium bifidum NK175, or their mix (LB101), which suppress the TNF-α to IL-10 expression ratio in macrophages, increase tear secretion and decrease keratitis and conjunctivitis in mice." (PMID 38885258, 2024). "House finches experience an influx of local and systemic pro-inflammatory cytokine production (IL-1β, IFN-γ, TNF-α) early in infection with MG, and individual variation in conjunctivitis is significantly predicted by individual variation in local IL-1β expression." (PMID 35707121, 2022). "Moreover conjunctivitis has shown a rise in inflammatory mediators (IL-1β, TNF-α, and MMP-9) and the activation of proinflammatory mitogen-activated protein kinase (MAP-K) pathways." (PMID 34615949, 2021). "These paradoxical functions of IL-10 reinforce our observation of increasing tear IL-10 in patients when compared with control subjects, and at the same time, an inverted IL-10/TNF-α ratio, approximating to the Th2/Th9 mediated inflammation reported in experimental conjunctivitis." (PMID 30818819, 2019).
cysticercosis (9 papers, 2014 to 2025). "Taken together, these data suggest that TNF-α blockade may provide a viable strategy to manage post-treatment pericystic inflammation that follows antiparasitic therapy for neurocysticercosis." (PMID 29190292, 2017). "Here, we show that microglia display a diminished expression of M1-inflammatory mediators such as tumor necrosis factor-alpha (TNF-α), interleukin-6 (IL-6), and nitric oxide synthase 2 (NOS2) in murine neurocysticercosis." (PMID 26148848, 2015). "Cysticercosis-positive individuals showed positive correlations between CD4 counts and pro-inflammatory cytokines (e.g., TNF-α, IL-1β), contrasting with negative correlations in cysticercosis-negative individuals." (PMID 40046043, 2025). "The interaction between cysticercosis status and HIV infection significantly decreased TNF-α (β = -0.574, p = 0.035) and IFN-γ levels (β = -0.577, p = 0.004), indicating that the coinfection may mitigate the increase typically observed with HIV alone." (PMID 39093864, 2024). "However, contrary to initial hypotheses, the coexistence of HIV with cysticercosis did not lead to significant alterations in the levels of TNF-α, IFN-γ, IL-5, and VCAM-1." (PMID 39093864, 2024). "However, no IL-6 and TNF-α secretion was detected after murine microglia were grown in the medium containing soluble factors from Mesocestoides corti metacestodes which are used as a murine model for neurocysticercosis." (PMID 27842570, 2016).
diabetic macular edema (9 papers, 2010 to 2025). "The authors suggest a larger trial to shed light on the efficacy of local or systemic TNF-blocking therapy in diabetic macular edema." (PMID 22737386, 2012). "Preliminary studies suggest a positive effect of intravenously administered TNF-α blockers, mainly infliximab, for treating refractory diabetic macular edema and neovascular age-related macular degeneration." (PMID 22737386, 2012). "TNF-α: Increased TNF-α levels in DR patients correlate with vascular endothelial dysfunction, capillary dropout, and BRB breakdown, leading to diabetic macular edema (DME)." (PMID 40722794, 2025). "Notably, TNF-α downregulates tight junction proteins of endothelial cells and it is also required for Vascular Endothelial Growth Factor (VEGF)-induced leakage, thus participating in the breakdown of the blood-retinal barrier (B), which is the main pathogenic factor of diabetic macular edema." (PMID 30127248, 2018).
dilatation (9 papers, 2008 to 2025). "Consequently, low FA levels will facilitate the ongoing inflammation and production of cardio-toxic cytokines, such as TNF alpha, leading to harmful consequences (LV dilatation, HF, mechanical complications)." (PMID 34575117, 2021). "This may give us insight as to the relative contribution of the RANK/RANKL and CaPO4 + TNFα osteoclastogenesis pathways in human aneurysmal disease, and thus inform future therapeutic interventions." (PMID 31546645, 2019). "Receiver operating characteristic (ROC) curves showed that IL-10 and TNF-α could distinguish bilateral ureteral dilatation in IRPF patients, with areas under the ROC curve (AUCs) of 0.813 (95% CI:0.607-1.000, p=0.026) and 0.950 (95% CI:0.856-1.000, p=0.001), respectively." (PMID 36524110, 2022). "Tumor necrosis factor alpha (TNF-α) overexpression induces apoptosis and leads to progressive ventricular dilatation and systolic dysfunction." (PMID 40558547, 2025). "According to the presence or absence of bilateral ureteral dilatation, the AUCs for IL-10 and TNF-α were 0.813 (sensitivity 0.900 and specificity 0.625, p=0.026) and 0.950 (sensitivity 0.900 and specificity 0.875, p=0.001), respectively." (PMID 36524110, 2022). "In 133 patients with IDC, the TNF-α genotype failed to predict either the severity of pump dysfunction and cardiac dilatation at baseline, or changes in pump function and cardiac dimensions after six months of medical treatment." (PMID 18997986, 2008). "Our findings support this selective ER stress pathway activation during AAA development, since VSMCs from human and murine aneurysmal disease display elevated levels of TNF-α signaling as well as PERK/eIF2α/ATF4 signaling, without corresponding changes in other ER stress pathways." (PMID 39846252, 2025).
Duchenne muscular dystrophy (9 papers, 2010 to 2025). Duchenne muscular dystrophy (DMD) is a neuromuscular disease characterized by rapidly progressive muscle weakness and wasting due to degeneration of skeletal, smooth and cardiac muscle. "Tumor necrosis factor (TNF)-α, a multi-functional cytokine, is elevated in muscle of patients with PM, DM and Duchenne’s muscular dystrophy, and expression of TNF-α correlates with levels of muscle regeneration." (PMID 24204966, 2013). "TNF-α plays a key inflammatory role in Duchenne muscular dystrophy (DMD)." (PMID 38396822, 2024). "Our data are consistent with a previous report showing that sildenafil, a vardenafil analogue, reduces fibrosis in the mdx mouse model of Duchenne muscular dystrophy: treating mdx mice with sildenafil reduced endomysial fibrosis and TNF-α overexpression in diaphragm." (PMID 23734196, 2013). "Finally, blockade of TNF-alpha in the dystrophic (mdx) mouse, which is the most frequently used model of Duchenne's muscular dystrophy, reduces TNF-mediated adverse responses to exercise-induced muscle damage." (PMID 22505941, 2012). "A mouse model of the fatal pediatric disease Duchenne muscular dystrophy (DMD) showed that TNF-mediated activation of JNK induces conformational changes in the insulin receptor substrate (IRS)-1, thereby disrupting downstream events after IGF-1/IGF-1 receptor binding." (PMID 35328423, 2022).
duodenal ulcer (9 papers, 2013 to 2022). An ulcer in the duodenal wall. "Epidemiological studies have evaluated the association between tumor necrosis factor α (TNF-α) single nucleotide polymorphisms (SNPs) and duodenal ulcer (DU), but the results remain inconclusive." (PMID 23451177, 2013). "The electroacupuncture group also had significantly reduced expression of TNF-α compared with the omeprazole group, further suggesting that pretreatment with electroacupuncture has an obvious inhibitory effect on the inflammatory response induced by stress ulcer." (PMID 33628315, 2021). "But, in the duodenal tissue of duodenal ulcer mice, although the expression of TNF-α increased, TRPV4 did not affect the expression of TNF-α in the tissue." (PMID 35028313, 2022).
Dysmenorrhea (9 papers, 2012 to 2025). Pain during menstruation that interferes with daily activities. "The authors demonstrated that the presence of the -308A TNFα allele can protect against dysmenorrhea and suggested that the TNFα-308, GG genotype may be a useful tool for predicting susceptibility to dysmenorrhea." (PMID 32069859, 2020). "Recent studies have shown that intensive aerobic exercises not only cause a reduction in the levels of the metabolite of prostaglandins (13,14-dihydro-15-ketoprostaglandin F2 alpha (KDPGF2α), but also reduce the level of TNFα, as well as reduce the intensity of pain associated with dysmenorrhea." (PMID 32069859, 2020). "The recent study investigated the effect of intensive exercise on dysmenorrhea alleviation as well as TNFα levels, prostaglandin metabolites, progesterone and selected interleukins." (PMID 32069859, 2020). "SFZYD has also been shown to effectively treat dysmenorrhea, a primary symptom of blood stasis, by regulating the expression of inflammatory cytokines, such as IL-1β, TNF-α, IL-10, IL-2 and IL-12, in a rat model." (PMID 28570676, 2017). "After the Great East Japan Earthquake, the relationship between dysmenorrhoea in Japanese adolescents was investigated, calling into question the higher levels of the cytokines TNF-α and IL-1 detected in PTSD patients, which could enhance the production of pain mediators." (PMID 34714186, 2021). "Another study on female with dysmenorrhea found that OEA supplement reduced malondialdehyde (MDA), c-reactive protein (CRP), and TNF-α significantly." (PMID 38778429, 2024). "Plasma IL6 and TNFα levels were found to be higher in women with dysmenorrhea compared to women without menstrual disorders." (PMID 32069859, 2020). "The effect of RCAS on PGF2 α, TNF-α, NO, Ca2+, and β - EP was not obvious, so the therapeutic effect of RCAS on dysmenorrhea was weaker than that of VCAS." (PMID 36176430, 2022).
Fabry disease (9 papers, 2013 to 2025). Fabry disease (FD) is a progressive, inherited, multisystemic lysosomal storage disease characterized by specific neurological, cutaneous, renal, cardiovascular, cochleo-vestibular and cerebrovascular manifestations. "Patients with Fabry disease also demonstrate an increase in T cell subsets and increased circulatory levels of pro-inflammatory cytokines, such as TNFα, IFNγ, IL1α, IL1β, IL6, and IL17." (PMID 39596318, 2024). "In this study, we were able to show that PPS reduces the secretion of TNFα and IL1β in a chemical in vitro model of Fabry disease to control levels." (PMID 31150494, 2019). "Serum, plasma, PBMCs, and several of the immune cells that include MOs, DCs, and NK cells have shown massive production of pro-inflammatory cytokines (e.g., IFNγ, TNF α, IL1β, and IL6) in patients with Fabry disease." (PMID 37189685, 2023). "There was a trend for low serum levels of IL-6 and high serum levels of TNF-α and high-sensitive CRP in Fabry patients; plasma concentrations of soluble VCAM-1 were significantly higher in Fabry disease patients than in healthy volunteers (p = 0.02)." (PMID 24207059, 2013).
fracture (9 papers, 2013 to 2025). "To check the status of immune response associated with hip fractures, we determined the serum TNF-α and IL-10 levels as well as the serum TNF-α/IL-10 ratio in rats at 24, 48, or 72 h after the hip fracture." (PMID 29357879, 2018). "Following a bone fracture, an inflammatory response is triggered, characterized by elevated levels of pro-inflammatory cytokines (IL-6 and TNF-α) released by neutrophils and macrophages." (PMID 40430554, 2025). "Our result showed that in elderly hip fracture rats, the serum levels of TNF-α and IL-10 were almost significantly increased compared with healthy controls, which was consistent with those previously reported." (PMID 29357879, 2018). "However, in C5aR2−/− mice, the concentrations of IL-1β, tumour necrosis factor (TNF) α and monocyte chemoattractant protein-1 (MCP-1) were significantly elevated after isolated fracture, indicating a pulmonary inflammatory response after bone fracture even in the absence of thoracic trauma." (PMID 29070810, 2017).
granulomatosis with polyangiitis (9 papers, 2011 to 2025). A small-vessel necrotizing vasculitis characterized by the association of inflammation of the vessel wall and peri- and extravascular granulomatosis. "In ANCA-associated vasculitis, CD28 was found to be downregulated on circulating and lesional CD4+ T- cells and CD4+CD28- T-cells have been described as the major source of pro-inflammatory cytokines (particularly IFN-γ and TNF-α) in Wegener’s Granulomatosis." (PMID 28991896, 2017). "The translation of TNF-α blockade (i.e., infliximab and etanercept) into a therapy for ANCA-associated GN (ANCA GN), including patients with granulomatosis with polyangiitis (GPA) (PR3-ANCA) and microscopic polyangiitis (MPO-ANCA), has faced challenges." (PMID 40735321, 2025). "Serum cytokine profile analysis in PAN patients has revealed an elevation in interferon-alpha (IFN-⍺), interleukine-2 (IL-2), tumor necrosis factor-α (TNF⍺), and IL-1-ß compared to healthy individuals and those with granulomatosis with polyangiitis (GPA)." (PMID 38068989, 2023). "In patients with granulomatosis with polyangiitis (GPA), monocytes have been shown to release high levels of IL-12 leading to induction of Th1 cytokines including TNF-alpha and IFN-gamma." (PMID 35747794, 2022).